ID2 (inhibitor of DNA binding 2)
Diseases named in the same sentence as ID2 in open-access papers (continued):
Sharing a sentence is not in itself a finding about the gene and the disease.
adenoma (1 paper, 2015). A neoplasm arising from the epithelium. "Id2 is highly expressed in the intestinal crypt epithelium and its expression level is further increased in Apc-deficient adenoma." (PMID 26163528, 2015). "β-catenin staining revealed that the percentage of Apc-deficient adenomas was ∼96% in Apc Id2 mice." (PMID 26163528, 2015). "We also found that tumor epithelial cells from adenomas larger than 0.5 mm in diameter showed essentially the same level of Id2 mRNA as that in microadenomas." (PMID 26163528, 2015). "Consistent with the qRT-PCR data, the levels of Id2 protein in ApcΔ716 adenomas were 3 times higher than that in the adjacent normal intestinal tissues." (PMID 26163528, 2015).
anaplastic large cell lymphoma (1 paper, 2020). Anaplastic large cell lymphoma (ALCL) is a rare and aggressive peripheral T-cell non-Hodgkin lymphoma, belonging to the group of CD30-positive lymphoproliferative disorders, which affects lymph nodes and extranodal sites. "Notably, increased levels of Id2 are also present in anaplastic large cell lymphomas that result from constitutive activation of the Midkine receptor, ALK." (PMID 31882403, 2020).
Atrophy (1 paper, 2009). Any weakening or degeneration, especially through lack of use. "The cytosolic content of Id2 is increased and is also positively correlated to apoptosis in rodent and bird models of unloading-induced atrophy." (PMID 19609365, 2009).
attention deficit-hyperactivity disorder (1 paper, 2018). A disorder characterized by a marked pattern of inattention and/or hyperactivity-impulsivity that is inconsistent with developmental level and clearly interferes with functioning in at least two settings (e.g. at home and at school). "Additionally, six genes displaying at least differential expression among hemispheres (BAIAP2, DAPPER1, LMO4, NEUROD6, ATP2B3, and ID2) in a case-control association study in an initial Spanish sample of ADHD (Attention Deficit Hyperactivity Disorder) patients and control subjects." (PMID 30081481, 2018).
biliary tract cancer (1 paper, 2023). "And similar to ID1 and ID3 proteins, ID2 is overexpressed in biliary tract cancer." (PMID 39130146, 2023).
bladder tumors (1 paper, 2022). "In human bladder tumors, the expression of ID2 and CDK1 is inversely related, and the combination of low ID2 and high CDK1 expression is associated with unfavorable clinical characteristics, including high tumor grade and muscularis propria invasion." (PMID 35729325, 2022). "Consistent with the expression of ID2, the CDK1 transcript level was dependent on tumor grade in BC, and CDK1 was upregulated in high-grade bladder tumors." (PMID 35729325, 2022). "Regarding the ID family genes, the expression of ID2, ID3, and ID4 but not ID1 was significantly lower in bladder tumors than in normal urothelium." (PMID 35729325, 2022).
brain injury (1 paper, 2019). Acute and chronic (see also brain INJURIES, CHRONIC) injuries to the brain, including the cerebral hemispheres, CEREBELLUM, and brain STEM. "This study demonstrates that the identified H19-miR-19a-Id2 axis plays a critical role in hypoxia induced neuronal apoptosis, and blocking this axis may serve as a novel therapeutic strategy for ischemic brain injury." (PMID 31170091, 2019).
breast tumors (1 paper, 2018). "While there is no consensus as to the prognostic impact of ID2 expression in breast tumors, relatively high ID1 expression has consistently been associated with poor prognosis and, consequently, with invasive and metastatic capacities." (PMID 29666142, 2018).
Cachexia (1 paper, 2021). Severe weight loss, wasting of muscle, loss of appetite, and general debility related to a chronic disease. "Due to its ability to bind to and inhibit MyoD and other myogenic regulatory factors, Id2 may be contributing significantly to the poor muscle outcomes seen in cachexia." (PMID 34806343, 2021).
Classical Hodgkin Lymphoma (1 paper, 2008). "Samples of classical Hodgkin lymphoma from 60 Chinese patients were analyzed for the expression of ID2, EBV-LMP1 and p16(INK4A) proteins by immunohistochemistry." (PMID 19099554, 2008).
COVID-19 (1 paper, 2025). A disease caused by infection with severe acute respiratory syndrome coronavirus 2. "CD8 T cells in both NALT and peripheral blood upregulated ID2 in acute and convalescent COVID-19, but upregulation of the long-term memory marker ID3 was significant only in convalescent patients." (PMID 39890933, 2025).
dilated cardiomyopathy (1 paper, 2023). Cardiomyopathy which is characterized by dilation and contractile dysfunction of the left and right ventricles. "In the CardiacMeso-fated segment, Myl7 and Id2 were reduced relative to controls, as was Ankrd1, a gene implicated in sarcomere-binding and dilated cardiomyopathy that is known to be upregulated with overexpression of Mesp1." (PMID 36994838, 2023).
experimental autoimmune encephalomyelitis (1 paper, 2022). An autoimmune demyelinating disease of the central nervous system that is produced experimentally in animals by the injection of homogenized brain or spinal cord in Freund's adjuvant. "In another study, Id2 was associated with increased activation phenotype of CD4 T cells under steady-state conditions, as well as IL17 production upon experimental autoimmune encephalomyelitis (EAE), an animal model of MS, induction, ultimately contributing to severe EAE pathogenesis." (PMID 35983065, 2022). "In an inflammatory setting, particularly in experimental autoimmune encephalomyelitis (EAE), elevated IL-1β and IL-6 mediated STAT3/IRF4/BATF signaling cascades promote Id2 activation." (PMID 35983065, 2022).
Flavivirus Infections (1 paper, 2018). Infections with viruses of the genus FLAVIVIRUS, family FLAVIVIRIDAE. "Further in-depth studies are warranted to elucidate the role of the host factors TMED2 and ID2 in flavivirus infection." (PMID 29451494, 2018).
gastric tumors (1 paper, 2019). "Id2 deficient (Id2−/−) mice developed gastric tumors and heterotopic squamous epithelium in the small intestine." (PMID 30984807, 2019).
Hydrocephalus (1 paper, 2022). Hydrocephalus is an active distension of the ventricular system of the brain resulting from inadequate passage of CSF from its point of production within the cerebral ventricles to its point of absorption into the systemic circulation. "Structural CNS anomalies have been associated with PVs in ID2 complex genes, microcephaly with PVs in FANCD1, FANCD2, FANCJ, ID2 complex, downstream genes, and hydrocephalus with FANCB genotype." (PMID 36091172, 2022).
Hyperinsulinemia (1 paper, 2023). An increased concentration of insulin in the blood. "Consistent with in vitro data, in vivo data show that ID2 expression increases in the placentas from obese dams lacking ASB4 with hyperinsulinemia." (PMID 36768469, 2023).
ileal tumor (1 paper, 2015). "In addition, the absence of Id2 in ileal tumor epithelium did not alter the proliferative capacity or the apoptosis rate in ApcΔ716 mice." (PMID 26163528, 2015).
influenza (1 paper, 2019). An acute viral infection of the respiratory tract, occurring in isolated cases, in epidemics, or in pandemics; it is caused by serologically different strains of viruses (influenzaviruses) designated A, B, and C, has a 3-day incubation period, and usually lasts for 3 to 10 days. "Published transcriptional profiles of NK cells, ILC1, and influenza-specific Id2-deficient mouse CD8+ T cells showed a striking concordance of Id2-dependent expression with our innateness gradient genes, highlighted by TBX21, ZEB2, IL18RAP, CCR7, TCF7, cytotoxicity, and KLR genes." (PMID 30737409, 2019).
insomnia (1 paper, 2021). A sleep disorder characterized by difficulty in falling asleep and/or remaining asleep. "Except for the reported findings, we found one set of genes including ID1, ID2, and ID3 was significantly enriched in biological processes of the circadian rhythm and speculated that insomnia in some PCOS patients may due to the abnormal expression of these genes." (PMID 34113617, 2021).
Intellectual disability (1 paper, 2019).
intestinal polyp (1 paper, 2015). Discrete abnormal tissue masses that protrude into the lumen of the intestine. "Expression of Id2 protein could not be detected in the normal intestinal tissues or intestinal polyps of the Apc Id2 mice." (PMID 26163528, 2015).
invasive breast carcinoma (1 paper, 2022). A carcinoma that infiltrates the breast parenchyma. "As such, E-cadherin and Id2 are promising candidates to stratify low and intermediate grade invasive breast cancers for the use of clinical cell cycle intervention drugs." (PMID 35437308, 2022). "We next analyzed a cohort of 148 invasive breast cancer samples and compared Id2 expression between IDC of no specific subtype (IDC-NST) and ILC using immunohistochemistry (IHC)." (PMID 35437308, 2022).
invasive ductal carcinoma (1 paper, 2022). "In our previous study, we found that ID2 promotes CSC self-renewal and its expression was critical for the transition of DCIS to invasive ductal carcinoma (IDC)." (PMID 35078502, 2022).
ischemia (1 paper, 2015). A hypoperfusion of the BLOOD through an organ or tissue caused by a PATHOLOGIC CONSTRICTION or obstruction of its BLOOD VESSELS, or an absence of BLOOD CIRCULATION. "No ID2+ or ID3+ cells were detected in the hippocampus proper (CA1-CA3) of both the sham-operated and the ischemia groups (data not shown)." (PMID 25503067, 2015).
lobular breast cancer (1 paper, 2022). "Together, these data show that in E-cadherin mutant lobular breast cancer cells, Id2 binds to hypo-phosphorylated (active) Rb to dampen cell cycle progression." (PMID 35437308, 2022).
malignant glioma (1 paper, 2019). A grade III or grade IV glioma arising from the central nervous system. "Interestingly, one of the correlated regions was the promoter of ID2, a transcriptional regulator that supports a pro-survival role in malignant gliomas by inactivating VHL." (PMID 31806013, 2019).
meningioma (1 paper, 2013). A generally slow growing tumor attached to the dura mater. "In line with the microarray data, real-time RT-PCR also showed statistically significant under-expression of LMO3 and ID2 in benignB and atypical meningioma with respect benignA meningioma." (PMID 23840654, 2013). "ID2 is another gene, closely related to transcription factors, which is highly down-regulated in metabolically aggressive meningioma." (PMID 23840654, 2013). "Homeobox protein Hox-B3 (HOXB3), LIM domain only protein 3 (LMO3), Homeobox protein Hox-B6 (HOXB6), Homeobox protein Hox-A3 (HOXA3) and DNA-binding protein inhibitor ID-2 (ID2) showed higher under-expression in benignB with respect benignA meningiomas with a fold change lower than −3." (PMID 23840654, 2013).
metastasis (1 paper, 2019). The spread or migration of cancer cells from one part of the body (where they first appeared) to another. "ID2 expression also associates with reduced brain metastasis relapse-free survival." (PMID 30642388, 2019).
mismatch repair deficiency (1 paper, 2022). "Of these, ID1 and ID2 are associated with polymerase slippage during DNA replication and found in large numbers in cancers with mismatch repair deficiency." (PMID 35168570, 2022).
myeloid leukemia (1 paper, 2017). A clonal proliferation of myeloid cells and their precursors in the bone marrow, peripheral blood, and spleen. "Many of those genes inhibited by SID peptide treatment (CD44, TGFβR2, LEF1, TCF7L2, FGF2, FGF5, ID2, PIK3R3) are known as direct TGIF1 targets in myeloid leukemia or embryonic stem cells." (PMID 29179446, 2017).
myocardial infarction (1 paper, 2019). Gross necrosis of the myocardium, as a result of interruption of the blood supply to the area, as in coronary thrombosis. "This study aimed to explore the effects of Id2 on cardiac fibrosis after myocardial infarction and its possible mechanisms." (PMID 31803053, 2019). "An animal myocardial infarction model was established by ligating of the left anterior descending coronary artery followed by directly injecting of Id2 adenovirus into the myocardial infarct’s marginal zone." (PMID 31803053, 2019).
myosarcoma (1 paper, 2019). "As the interaction network of upregulated and downregulated miRNAs displays, we found that FOS, TGFB1, RB1 and ID2 are important genes controlling proliferation and apoptosis in myosarcoma." (PMID 30717351, 2019).
orchitis (1 paper, 2021). Inflammation of one or both testes due to viral or bacterial infections. "On the other hand, Klf2, Klf4, Nfe2l2/Nrf2, Id1, Id2, Rad21, Xrcc1, and Cycs were found to be negatively correlated with androgen synthesis during orchitis." (PMID 35111154, 2021).
osteoporosis (1 paper, 2023). A condition of reduced bone mass, with decreased cortical thickness and a decrease in the number and size of the trabeculae of cancellous bone (but normal chemical composition), resulting in increased fracture incidence. "It upregulates the expression of the RNAKL repressor Id2, which was also demonstrated in female patients with osteoporosis whose serum IL-27 levels were reduced along with decreased Egr2 expression, suggesting a potential new anti-osteoporosis treatment strategy." (PMID 37475866, 2023).
pancreatic adenocarcinoma (1 paper, 2023). "The pan-cancer survey of distinct tumor types from patients revealed that TRIM69 was recurrently upregulated in nearly all tumors including pancreatic adenocarcinoma (PAAD), which also contained much higher levels of Ctnnb1 and Id2 than the normal controls." (PMID 36741265, 2023).
pancreatic ductal adenocarcinoma (1 paper, 2018). An infiltrating adenocarcinoma that arises from the epithelial cells of the pancreas. "Our previous study also revealed that EYA4 expression is repressed in human pancreatic ductal adenocarcinoma and mediates tumor-suppressive effects by abolishing the β-catenin Ser675-dependent transactivation of inhibitor of DNA binding 2 (ID2)." (PMID 29764501, 2018).
periodontitis (1 paper, 2022). An acute or chronic inflammatory process that affects the tissues that surround and support the teeth. "Periodontitis in adults resulted in decreased levels of CSNK1D, RORA, CLOCK, DBP, NR1D1, ID2, and PER3 and a substantial increase in expression of FOS." (PMID 36472983, 2022).
pregnancy disorder (1 paper, 2024). A disorder that is related to pregnancy. "The dysregulation of ID2-mediated IGF-1 signaling in trophoblast cells could be involved in the pathogenesis of pregnancy disorders like uterine growth restriction and PE." (PMID 39768370, 2024).
primary effusion lymphoma (1 paper, 2023). A large B-cell lymphoma located in the body cavities, characterized by pleural, peritoneal, and pericardial fluid lymphomatous effusions and that is always associated with human herpes virus-8 (HHV-8). "Our group has recently shown that RTA induces the degradation of ID2 during lytic reactivation of KSHV in primary effusion lymphoma (PEL) cells." (PMID 36992439, 2023).
pulmonary hypertension (1 paper, 2020). Increased pressure within the pulmonary circulation due to lung or heart disorder. "In a further replication test on an independent cohort, only ID2 was validated and in an additional animal study, ID2 expression was significantly upregulated in mice with HFpEF and pulmonary hypertension compared to control mice." (PMID 33308225, 2020).
retinal hemangioblastoma (1 paper, 2019). A hemangioblastoma that arises from the retina.
sarcopenia (1 paper, 2009). Progressive decline in muscle mass due to aging which results in decreased functional capacity of muscles. "In conclusion, our current data provide an explanation for previous observations indicating that cytoplasmic levels of Id2 and nuclear apoptosis are increased under conditions of muscle wasting including sarcopenia." (PMID 19609365, 2009).
seminoma (1 paper, 2025). A radiosensitive malignant germ cell tumor found in the testis (especially undescended), and extragonadal sites (anterior mediastinum and pineal gland). "Intriguingly, ID signatures (ID1, ID2, and ID9) were significantly associated with DNA replication stress exclusively in seminomas, consistent with prior reports implicating replication-associated DNA damage in TGCT pathogenesis." (PMID 40568177, 2025).
squamous cell lung carcinoma (1 paper, 2020). A carcinoma arising from squamous bronchial epithelial cells. "Furthermore, in the Hou dataset it was demonstrated that the expression level of ID2 was decreased in squamous cell lung carcinoma, with a fold change of -2.485." (PMID 32003423, 2020).
thyroid (1 paper, 2014). "The expression level of ID2 mRNA in the liver exhibited a dose-dependent increase, indicating that this ID isotype might serve as sensitive and stable indicator for thyroid-disrupting chemical (TDC) exposure." (PMID 25090620, 2014).